PPARG (peroxisome proliferator activated receptor gamma)
Diseases named in the same sentence as PPARG in open-access papers (continued):
Sharing a sentence is not in itself a finding about the gene and the disease.
bladder cancer (continued). "In this review, we closely examine the TZD class of drugs and their effects on PPARγ in patient studies along with additional molecular factors that are positive modulators, such as protein phosphatase 5 (PP5), which may have considerable implications for bladder cancer therapy." (PMID 28348577, 2017). "Although our previous studies revealed that Nuclear protein 1 acts as an oncogene in bladder cancer, and the carcinogenic role may be achieved through EMT, the crosstalk of Nuclear protein 1 and PPARG in bladder cancer has not been fully elucidated." (PMID 37197716, 2023).
hepatocellular carcinoma (114 papers, 2001 to 2026). A malignant tumor that arises from hepatocytes. "To explore the association between PPARG expression and frequent somatic mutations, we analyzed 17 datasets of hepatocellular carcinoma and pancreatic cancer from the cBioprotal database, as well as two datasets of pan-cancer." (PMID 38044948, 2023). "In the liver, the level of PPARγ is low, however it is implicated in several pathologies and its activation leads to a diminution of hepatocellular cancer growth by induction of cell apoptosis." (PMID 23094162, 2012). "PPARγ activation in these macrophages has been directly linked to their ability to promote hepatocellular carcinoma (HCC) cell migration, invasion, and tumour angiogenesis." (PMID 40395129, 2025). "A recent study has also linked the antineoplastic role of 15d-PGJ2 in the HBV-associated HCC (Hepatitis B Virus-associated Hepatocellular Carcinoma) growth and the activation of PPARγ." (PMID 23094162, 2012). "Similar mechanisms have been described in hepatocellular carcinoma, where PPARγ activity can be co‐opted by aggressive tumors to support immune evasion in nutrient‐scarce microenvironments." (PMID 41236441, 2025). "In the Yoshida AH-130 hepatoma rat model, these changes were reversed by β2-agonist treatment, suggesting that PPARγ contributes to muscle metabolic reprogramming and atrophy." (PMID 41476922, 2025). "Previous studies have shown that USP22 stabilizes PPARγ in hepatocellular carcinoma to regulate lipidome accumulation." (PMID 40448065, 2025). "In contrast, other studies suggest that PPARγ agonizts inhibit cancer cell proliferation in lung adenocarcinoma and hepatocellular carcinoma." (PMID 39695138, 2024). "After PGZ treatment, PPARγ expression in hepatoma cells was elevated and the growth and invasion of HCC cells were inhibited by blocking RAGE signaling." (PMID 37251321, 2023). "Ectopic overexpression of peroxisome-proliferator-activated receptor-gamma (PPARγ) co-activator-1alpha in the hepatoma line further enhances the abundance of SREBP1c mRNA in an LXR/RXR-dependent manner." (PMID 36969840, 2023). "In hepatocellular carcinoma, β-estradiol (E2) activates PPARγ in cancer cells, and activated PPARγ inhibits cell invasion by upregulating the expression of PAI-1." (PMID 37251321, 2023). "miR-27: Early studies suggested that miR-27a decreases lipid accumulation in rat HSCs and human hepatoma cells by targeting the retinoid X receptor alpha and impairs adipocyte differentiation by targeting PPARγ." (PMID 37190114, 2023). "In hepatocellular carcinoma cells, PPARγ activation using rosiglitazone, or its overexpression, induced Cited2, which was associated with reduced cell growth and the induction of p15, p21, and p27." (PMID 35954274, 2022). "A good study by Schaefer and colleagues using hepatocellular carcinoma cells demonstrated that PPARγ antagonists prevented adhesion to the extracellular matrix followed by caspase-dependent apoptosis (anoikis)." (PMID 35954274, 2022). "In particular, curcumin phytosome supplementation induced PPARγ and reduced NFkB in a transgenic mouse model of hepatitis B virus-related hepatocellular carcinoma." (PMID 35011106, 2022). "When ERα works together with ERβ, they show an inhibitory role on PPARγ, which promoting the proliferation of hepatocellular carcinoma cells." (PMID 36060947, 2022). "To clearly elucidate the relationship between the AMPK-TBC1D1 axis and PPARγ, we constructed a relevant system in human hepatoma cell line (HepG2), human embryonic kidney cell line (HEK293T), and primary hepatocytes." (PMID 35061665, 2022). "Treatment of hepatoma cells with fatty acids and ethanol upregulates SREBP1c and PPARγ, and downregulates SIRT1, leading to impaired fatty-acid oxidation." (PMID 33747521, 2021). "PFKFB4 was required for peroxisome proliferator-activating receptor γ (PPARγ)-stimulated glycolysis in hepatocellular carcinoma." (PMID 33593309, 2021).
hepatocellular carcinoma (continued). "The abundance of FTX is thought to influence cell viability, invasion, and aerobic glycolysis of hepatocellular carcinoma cells by regulating the PPARγ pathway." (PMID 33817286, 2020). "MiR-27a has also been demonstrated to repress the activity of PPARγ in hepatocellular carcinoma cells." (PMID 29416678, 2018). "Two PPARγ activators PGJ2 and pioglitazone were reported to induce apoptosis by decreasing Bcl-2 in chronic hepatitis B-associated hepatocellular carcinoma cells." (PMID 30018246, 2018). "PPARγ is expressed in normal hepatocytes, nonalcoholic fatty liver cells, hepatocellular carcinoma tissues, and various liver cancer cell lines." (PMID 29483923, 2018). "SEPT2 downregulation was shown to suppress hepatoma cell growth by PPARγ (Peroxisome proliferator-activated receptor gamma) activation." (PMID 29724999, 2018). "In hepatoma HepG2 cells, miR-122 was strongly induced in cells treated with DNA methylation or histone deacetylase inhibitors via a direct binding of PPARγ/RXRα in the pre-miR-122 promoter." (PMID 28167956, 2017). "This indicates that celecoxib can up-regulate PTEN mediated activation and up-regulation of PPARγ in hepatoma cells." (PMID 24721996, 2014). "Pharmaceutical modulators of PPARγ signaling were used to confirm the role of PPARγ in celecoxib-induced PTEN upregulation in hepatoma cells." (PMID 24721996, 2014). "In this study, we found that PPARγ agonists inhibited the cancer stem cell-like phenotype and attenuated tumor growth of human hepatocellular carcinoma (HCC) cells." (PMID 24023668, 2013). "The expression of PPARγ varies in hepatocellular carcinoma and is reported to be at the same level, a higher level, or a lower level in comparison with normal liver." (PMID 23316217, 2012). "It has been reported that PPARγ inhibits hepatocellular carcinoma and other carcinomas in many vitro studies." (PMID 23316217, 2012). "The aim of the present study was to identify changes in gene expression profiles induced by PPARγ and PPARα/γ agonists in human hepatocytes from several donors and in differentiated human hepatoma HepaRG cells using a whole genome transcriptomic approach." (PMID 21533120, 2011). "PPARγ targets cyclin D1 via the inhibitors ofcyclin-dependent kinases (Cdk), p18, p21, and p27, causing a decline in Rb phosphorylation and arresting cells in G1phase: PPARγ acts via p21 and p27 in pancreaticcancer and via p18 in hepatoma." (PMID 19043603, 2008). "It has been reported that PPARγ inhibitors prevented thyroid and hepatocellular carcinoma cell adhesion by inhibition of FAK phosphorylation and inducing cell death by anoikis." (PMID 18261208, 2008). "In previous work, we reported the involvement of PPARγ in tumor-cellproliferation and differentiation in hepatoma and lung tumor cells." (PMID 17389773, 2007). "15(S)-HETE drives peritoneal macrophages toward an anti-tumor phenotype via the PPARγ/C/EBPβ axis, while genipin inhibits CCR2 signaling through PPARγ-mediated p65 degradation, reducing macrophage infiltration and preventing hepatocellular carcinoma recurrence." (PMID 41459510, 2025). "PPARγ is a protective factor in liver cancer by some mechanisms, including inhibiting hepatic fibrosis progression and inflammation, suppressing tumor microenvironment remodeling, and promoting apoptosis and senescence in hepatocellular carcinoma (HCC) cells." (PMID 41378310, 2025). "Recent research has highlighted the involvement of PPARG in regulating lipid degeneration and promoting neutrophil infiltration in the liver during the transition from inflammatory liver disease and fatty liver to hepatocellular carcinoma." (PMID 38044948, 2023). "Moreover, miR-27a directly targets the 3′-UTR of the Pparγ gene to promote proliferation of hepatocellular carcinoma cells." (PMID 37190114, 2023).
hepatocellular carcinoma (continued). "In examining PPARγ expression between cancer cells and healthy control cells, we observed significantly higher PPARγ expression in the four hepatocellular carcinoma cell lines (LM3, HLF, Huh7, and Hep G2) compared to the two normal liver cell lines (LO2 and L68)." (PMID 38044948, 2023). "Resistance to 5-fluorouracil (5-FU) is the main cause of chemotherapy failure in advanced hepatocellular carcinoma, and ROSI activation of PPARγ increases PTEN expression and decreases COX-2 expression, inducing sensitivity to 5-FU antitumor activity in HCC cell lines." (PMID 37251321, 2023). "However, contrary to the CAFs-dependent pro-tumor properties, PPARγ reduces hepatoma cell metastasis by inhibiting the transcriptional activity of MMPs and smad family member 3 (SMAD3), thereby reducing hepatoma cell metastasis." (PMID 37251321, 2023). "PPARγ transcriptional activity is inhibited by activated AMPK in hepatoma cells." (PMID 36114448, 2022). "However, an in vitro study suggested that PPARγ antagonists inhibited metastasis through the cleavage of vimentin in hepatocellular carcinoma." (PMID 35954274, 2022). "In addition, ERα and ERβ inhibit transcription and translation of peroxisome proliferator-activated receptor γ (PPARγ) gene in a ligand-dependent manner, and PPARγ can promote the proliferation of hepatocellular carcinoma cells." (PMID 36060947, 2022). "LncRNA-Ftx via targeting GLUTs through the PPARγ pathway could promote aerobic glycolysis in hepatocellular carcinoma." (PMID 33123468, 2020). "Moreover, miR-27a suppressed lipid accumulation in rat hepatic stellate cells and human hepatoma cells by targeting retinoid X receptor α and impair adipocyte differentiation by targeting PPARγ." (PMID 31930115, 2019). "A series of current papers indicate that, due to the differences in metabolic environment, cell types, and carcinogenic signal pathways, PPARγ may be expressed as either inhibiting or promoting the growth and proliferation of the hepatocellular carcinoma." (PMID 29483923, 2018). "In addition, this statement corroborates the finding that PPARγ downregulation induced autophagy in hepatocellular carcinoma." (PMID 29201005, 2017). "The role of PPARγ in hepatocellular carcinoma is still debated." (PMID 28115925, 2016). "However, the role of PPARγ, which regulates tumour promoter and oncogene expression, is not well understood in hepatocellular carcinoma (HCC)." (PMID 27769068, 2016). "Most interestingly, there have been encouraging reports revealing that PPARγ activation prevents cancer in tissues such as colon, breast, prostate, lung and liver, justifying that PPARγ agonists may be useful in hepatocellular carcinoma therapy." (PMID 27769068, 2016). "PPARγ could play a tumor-promoting role in hepatoma, because expression is significantly reduced in hepatocellular carcinoma with poor prognosis." (PMID 25866814, 2015). "The possible long-term treatments of differentiated normal and steatotic human hepatoma HepaRG cells could represent a unique way to better understand hepatotoxicity of PPARγ agonists." (PMID 20981297, 2010). "Recent studies have demonstrated that PPARγ agonists may induce growth inhibition in hepatocellular carcinoma (HCC) cells in a dose- and time-dependent manner." (PMID 15467764, 2004). "In addition, increased IL-32β expression has been reported to decrease intracellular lipid concentrations in hepatoma cells, which may be mediated by reduced PPARγ expression and elevated AMPK activity." (PMID 37686029, 2023). "In particular, Liu and Colleague showed that PPARγ agonists inhibited the cancer stem cell-like phenotype and decreased tumor growth of human hepatocellular carcinoma (HCC) cells." (PMID 34204425, 2021). "In hepatocellular carcinoma (HCC) patients, reduced PPARγ was detected in human tumor-infiltrating iNKT cells, in comparison to cells in para-carcinoma tissues." (PMID 31974378, 2020).
hepatocellular carcinoma (continued). "LncRNA Ftx has been described as a regulator of peroxisome proliferator-activated receptor γ (PPARγ) pathway in hepatocellular carcinoma (HCC)." (PMID 31191327, 2019). "However, the role of PPARγ in hepatocellular carcinoma (HCC) remains controversial." (PMID 27483249, 2016). "In this study, expression of PPARγ in human hepatocellular carcinoma (HCC) and the effect of PPARγ ligands on HCC cells were investigated in vitro using Hep G2, HuH-7, KYN-1 and KYN-2 cell lines." (PMID 11401318, 2001). "USP22 deubiquitinates and enhances the stability of PPARγ protein, thereby promoting the synthesis of FASN, ACLY, and ACACA, and facilitating the malignant progression of hepatocellular carcinoma." (PMID 39944823, 2025). "Recent research hinted at the relationship between CMTM3 and PPARγ, whereby the pro-tumorigenic effects of CMTM3 in hepatocellular carcinomas involve the modulation of PPARγ." (PMID 40697995, 2025). "Ubiquitin-specific protease 22 (USP22) stabilizes PPARγ due to deubiquitination, which increases acetyl-CoA carboxylase (ACC) and ATP citrate lyase (ACLY) expression and induces de novo lipogenesis as a risk factor for hepatocellular carcinoma (HCC)." (PMID 35954274, 2022). "Peroxisome proliferator-activated receptor-γ (PPARγ) activation has been observed to exert a protective effect against IRI and IRI-induced metastasis of hepatocellular carcinoma." (PMID 33122687, 2020). "A previous study found that miR-27a regulated many lipid metabolism-related transcription factors, including RXRα, PPARγ, FASN, SREBP1, and SREBP2 in human hepatoma cells." (PMID 29445089, 2018). "Immunoblot analysis revealed that expression of PPARγ and PTEN was significantly upregulated as well as Akt was dephoshorylated in celecoxib-treated hepatoma tissues." (PMID 24721996, 2014). "Treatment with rosiglitazone, a PPARγ agonist, increased the endogenous and celecoxib-induced PTEN protein levels in hepatoma cells." (PMID 24721996, 2014). "Furthermore, TNFα and IL1β treatment of Hep3B human hepatoma cells and mice resulted in decreased expression of RXRα, PPARα, PPARγ, LXRα, as well as their co-activators PGC1α and PGC-1β, which may contribute to the cytokine induced modulations in hepatic energy homeostasis." (PMID 24112857, 2013). "This wasdescribed in primary esophageal tumor specimen and in esophageal cancer celllines, in human primary squamous cellcarcinoma (SCC) and lymph node metastases and in hepatocellular carcinoma(HCC) samples, where PPARγ expression is elevated compared tomatched normal tissue." (PMID 18596912, 2008). "In addition, hispidulin activates PPARγ through the activation of AMPK and ERK signaling pathways to inhibit hepatocellular carcinoma growth and metastasis both in vitro and in vivo." (PMID 33324687, 2020). "In hepatocellular carcinoma, immunostainingalso demonstrates that PPARγ isoverexpressed in all of 20 carcinoma tissues but not in normal hepatocytes." (PMID 18784849, 2008). "In hepatocellular carcinoma (HCC), PPARγ, phosphorylated at Ser84, promoted PFKFB4 transcription, thereby promoting glycolysis to maintain HCC progression." (PMID 37024456, 2023). "Hispidulin can activate PPARγ through the activation of adenosine 5′-monophosphate (AMP)-activated protein kinase (AMPK) and extracellular regulated protein kinases (ERK) signaling pathways, thereby suppressing the oncogenesis and metastasis of hepatocellular carcinoma both in vitro and in vivo." (PMID 33324687, 2020). "Moreover, celecoxib has been reported to stimulate PPARγ as well as PTEN, the endogenous antagonist of Akt signaling, in hepatoma cells, we investigated whether this signaling pathway affects the therapeutic mechanism of celecoxib for Novikoff hepatoma." (PMID 24721996, 2014).
hepatocellular carcinoma (continued). "Although cross-talk of PPARγ,but not PPARα, with cyclooxygenase 2 (Cox-2), which also was relatedwith inflammation-induced hepatocellular carcinoma, has been suggested, there was neither induction ofCox-2 nor PPARγ in both genotyped mice of that study (datanot shown)." (PMID 18769559, 2008).